NR5A2 (nuclear receptor subfamily 5 group A member 2)
Diseases named in the same sentence as NR5A2 in open-access papers (continued):
Sharing a sentence is not in itself a finding about the gene and the disease.
hepatocellular carcinoma (7 papers, 2015 to 2024). A malignant tumor that arises from hepatocytes. "A study on hepatocellular carcinoma showed that the downregulation of NR5A2 expression using gene silencing technology inhibits the process of cell proliferation." (PMID 38358044, 2024). "Recent research findings have confirmed the involvement of NR5A2 in the genesis and development of multiple tumor types, including esophageal and lung squamous tumors; breast, pancreatic, and gastric cancers; and hepatocellular carcinomas." (PMID 38358044, 2024). "The nuclear receptor liver receptor homolog 1 (LRH-1) (also known as NR5A2) was recently found to have a regulatory role in hepatoma formation, since it was shown to upregulate mitochondrial ALT2/GPT2 and cytosolic AST1/GOT1 aminotransferase isoforms as well as glutaminase 2 (GLS2)." (PMID 30416487, 2018).
lung cancer (7 papers, 2017 to 2024). A malignant neoplasm involving the lung. "Here, we showed the diagnostic and prognostic values of elevated Nr5a2 expression in human lung cancer." (PMID 30740909, 2019). "Nr5a2 amplification, observed in lung cancer tissues (6A‐B), is associated with poor OS and PFS (6C ‐D)." (PMID 30740909, 2019). "Hence, the diagnostic, prognostic, and therapeutic potential of Nr5a2 in lung cancer merits further investigation." (PMID 30740909, 2019). "To determine the clinical relevance of Nr5a2 in human lung cancer, we analyzed the copy number of Nr5a2 between lung adenocarcinoma and normal lung tissues using Oncomine database." (PMID 30740909, 2019). "We genotyped the seven 3′UTR SNPs in NR5A2, LPP, and TNS3 to determine the potential association with the susceptibility to lung cancer." (PMID 30621612, 2019). "First, the prognostic value of Nr5a2 overexpression in human lung cancer has been evaluated and established." (PMID 30740909, 2019). "In one study of lung adenocarcinomas, elevated expression levels of NR5A2 negatively correlated with overall survival, while in another study of non‐small cell lung cancer, elevated expression levels of NR5A2 positively correlated with distant metastatic events." (PMID 38358044, 2024). "In addition, NR5A2 is a direct target for microRNA‐376c to inhibit cell proliferation and invasion via Wnt signaling pathway in nonsmall cell lung cancer." (PMID 36303447, 2022). "NR5A2 has been shown to promote lung cancer development and progression by upregulating Nanog." (PMID 34277436, 2021). "This set of observations suggests that Nr5a2 promotes human lung cancer progression." (PMID 30740909, 2019). "Given the essential role of Nr5a2 in regulating LLC‐SD self‐renewal activity in vitro, we conducted xenograft transplantation assay in nude mice to investigate the importance of Nr5a2 in lung cancer tumorigenesis." (PMID 30740909, 2019).
colon cancer (6 papers, 2015 to 2022). "In particular, Nr5a2 knockdown in colon cancer cell lines leads to an impairment in cell proliferation." (PMID 34034704, 2021). "Recent work has shown that the silencing of Nr5a2 in colon cancer cell lines affects signal transduction, GTPase activity, cholesterol transport, and apolipoprotein expression." (PMID 26518232, 2015). "It this study, we found the consistent results by showing that NR5A2, PPARGC1A and LGALS4 were down-regulated in colon cancer cell lines and downregulation of the three genes were related to poor prognosis." (PMID 36440228, 2022). "We found that NR5A2, PPARGC1A and LGALS4 were all down-regulated in colon cancer cell lines, in comparison with normal colon epithelial cell line." (PMID 36440228, 2022).
glioma (6 papers, 2018 to 2024). A benign or malignant brain and spinal cord tumor that arises from glial cells (astrocytes, oligodendrocytes, ependymal cells). "We investigated the mechanism of NR5A2 underlying malignant progression of glioma through assays and further studied the sensitivity of glioma to cisplatin, laying groundwork for future clinical diagnosis and management." (PMID 36303447, 2022). "MicroRNA‐433‐3p plays a tumor repressor role in glioma by targeting NR5A2, thus regulating cell behaviors, and enhancing chemosensitivity to cisplatin." (PMID 36303447, 2022). "(2020) manifested that aberrant level of NR5A2 results in unfavorable clinical prognosis and overall survival of patients, and upregulation of NR5A2 enhances cell resistance to temozolomide glioma." (PMID 36303447, 2022). "Bioinformatics analysis was used to identify the upstream microRNA of NR5A2 in glioma, while dual‐luciferase and western blot assays were used to detect binding of microRNA and NR5A2." (PMID 36303447, 2022). "After upregulating microRNA‐433‐3p level in glioma cell line U87, microRNA‐433‐3p decreased NR5A2 level." (PMID 36303447, 2022). "Rescue experiments also indicated that microRNA‐433‐3p suppressed glioma malignant progression via inhibiting NR5A2." (PMID 36303447, 2022). "We manifested that NR5A2 was activated in drug‐resistant glioma cell line while silencing NR5A2 notably inhibiting cell resistance to cisplatin." (PMID 36303447, 2022). "Although NR5A2 plays a pivotal role in affecting tumor cell chemosensitivity, the role of NR5A2 in glioma and its molecular mechanism are still unclear." (PMID 36303447, 2022). "In this study, NR5A2 was taken as the object of interest, and its biological role in progression of glioma was clarified." (PMID 36303447, 2022). "Quantitative reverse transcriptase PCR (qRT‐PCR) and western blot were utilized to assess NR5A2 mRNA and protein expression in different glioma cell lines, respectively." (PMID 36303447, 2022). "MicroRNA‐433‐3p hindered malignant progression of glioma via binding NR5A2 and enhanced glioma chemosensitivity to cisplatin." (PMID 36303447, 2022). "Herein, we proved that the expression of NR5A2 was negatively correlated with that of microRNA‐433‐3p in glioma and confirmed that NR5A2 was the direct target of microRNA‐433‐3p by luciferase reporter assay." (PMID 36303447, 2022). "MicroRNA‐433‐3p which is significantly poorly expressed in glioma targets NR5A2 to suppress glioma malignant progression and enhance chemosensitivity to cisplatin." (PMID 36303447, 2022). "MTT, Transwell assay, and flow cytometry were carried out to assay the impact of NR5A2 on behaviors of glioma cells in vitro." (PMID 36303447, 2022). "Transwell assay result denoted that overexpression of microRNA‐433‐3p noticeably hampered cell invasion and migration induced by NR5A2, and to some extent rescued promoting impact of NR5A2 on the cell invasion and migration of glioma (p < 0.05)." (PMID 36303447, 2022). "The glioma data downloaded from the TCGA database indicated that NR5A2 was significantly increased in glioma tissue, and survival analysis result showed that patients with high NR5A2 expression in glioma suffered poor prognosis." (PMID 36303447, 2022). "MTT assay was used to investigate the impact of NR5A2 on chemosensitivity of glioma cells to cisplatin." (PMID 36303447, 2022). "Cell assays revealed that silencing NR5A2 could hamper proliferation, invasion, and migration and enhance chemosensitivity to cisplatin while promoting glioma cell apoptosis and blocking glioma cells in G0/G1 phase." (PMID 36303447, 2022). "NR5A2 was upregulated in both glioma tissues and cell lines." (PMID 36303447, 2022). "si‐NR5A2 was transfected into glioma cells HS683 and U87, respectively." (PMID 36303447, 2022). "MTT assay was used to assess the impact of NR5A2 on proliferative ability of glioma cells." (PMID 36303447, 2022).
glioma (continued). "Further studies showed that NR5A2 could promote cell proliferation and tumor growth via Notch signaling pathway, suggesting that it might be a novel target for immunotherapy in glioma." (PMID 35285582, 2022). "Collectively, NR5A2 could facilitate glioma cell malignant progression and enhance cell resistance to cisplatin." (PMID 36303447, 2022). "Despite the finding that microRNA‐433‐3p could restrain glioma progression via targeting NR5A2, other targets of microRNA‐433‐3p may also affect the carcinogenesis of gliomas." (PMID 36303447, 2022). "When the concentration of cisplatin was 1, 2, and 4 μg/ml, cell viability of HS683/DDP and U87/DDP with silencing NR5A2 was notably lower than that of the si‐NC group, showing that silencing NR5A2 noticeably increased chemosensitivity of glioma cells to cisplatin (p < 0.05)." (PMID 36303447, 2022). "Moreover, silencing NR5A2 hindered cell cycle progress, proliferation, invasion, and migration of glioma cells and induced cell apoptosis." (PMID 36303447, 2022). "In addition, we found that NR5A2 level in glioma resistant cell lines HS683/DDP and U87/DDP was conspicuously higher than that in its parental cells (p < 0.05)." (PMID 36303447, 2022). "Cisplatin chemosensitivity assay showed that forced expression of microRNA‐433‐3p in HS683/DDP cell line markedly promoted sensitivity of glioma cells to cisplatin, while NR5A2 could reverse the promotion of microRNA‐433‐3p on glioma cell sensitivity to cisplatin." (PMID 36303447, 2022). "Thus, microRNA‐433‐3p may enhance chemosensitivity of glioma to cisplatin via modulating cell cycle distribution, activating cell apoptosis, and downregulating NR5A2 level." (PMID 36303447, 2022). "Pearson correlation analysis revealed that NR5A2 and microRNA‐433‐3p had the highest Pearson correlation coefficient, suggesting that microRNA‐433‐3p might be able to target NR5A2 to regulate the malignant progression of glioma." (PMID 36303447, 2022). "NR5A2 via regulating notch signal pathway could promote cell growth and resistance to TMZ in glioma." (PMID 34178658, 2021).
pancreatitis (6 papers, 2015 to 2024). Inflammation of the pancreas. "NR5A2 is an important regulator of exocrine function in the adult pancreas where it maintains homeostasis and promotes regeneration of acinar cells after inflammation caused by chemically induced pancreatitis, and protects the pancreas from KRAS driven pre-neoplastic changes." (PMID 27579533, 2016). "Recent evidence suggests that NR5A2 could contribute to PDAC through a role in the recovery from pancreatitis-induced damage." (PMID 25742499, 2015).
gastric cancer (5 papers, 2014 to 2024). A primary or metastatic malignant neoplasm involving the stomach. "Thus, this study was conducted, and it indicates that the NR5A2 polymorphism is significantly associated with the development and overall survival of gastric cancer." (PMID 25514243, 2014). "Therefore, we conducted this study to examine whether NR5A2 rs3790844 and rs3790843 polymorphisms are associated with clinical outcomes of gastric cancer." (PMID 25514243, 2014). "Finally, for validation of the genotype–phenotype relationship, further investigation is underway to clarify the association between rs3790843 and rs3790844 polymorphisms and expression levels of NR5A2 protein in gastric cancer tissues, and will be reported separately." (PMID 25514243, 2014). "Among 944 specimens from patients with gastric cancer, NR5A2 rs3790843 was successfully genotyped in 907 specimens, and NR5A2 rs3790844 was successfully genotyped in 912 specimens." (PMID 25514243, 2014). "In a study of gastric cancer, cancer cell proliferation was inhibited after NR5A2 silencing." (PMID 38358044, 2024). "However, it seemed no study focused on the association between NR5A2 and the progression and prognoses of gastric cancer." (PMID 25514243, 2014). "In addition, overexpression of NR5A2 was shown to promote the proliferation of gastric adenocarcinoma SGC-7901 cells via induction of cyclin E1, which may lead to the tumorigenesis of gastric cancer." (PMID 25514243, 2014).
breast tumors (4 papers, 2014 to 2024). "The immunohistochemistry (IHC) stain of NR5A2 is elevated in breast tumors and is preferentially coexpressed with ERα." (PMID 26366408, 2015). "Lastly, NR5A2 is regulated by ER in luminal breast tumors, demonstrating that hormonal regulation may influence NR5A2 activity." (PMID 38994678, 2024).
pancreatic ductal adenocarcinoma (4 papers, 2014 to 2024). An infiltrating adenocarcinoma that arises from the epithelial cells of the pancreas. "NR5A2 is mainly expressed in the pancreas and liver, making it an attractive target for selectively inhibiting SOX2 in pancreatic ductal adenocarcinoma (PDAC)." (PMID 38012687, 2023). "However, the role of NR5A2 and the specific regulatory mechanism of NR5A2 in pancreatic ductal adenocarcinoma (PDAC) are not thoroughly studied." (PMID 33850096, 2021).
acute pancreatitis (3 papers, 2019 to 2024). An acute inflammatory process that leads to necrosis of the pancreatic parenchyma. "However, the cytological and molecular evidence regarding how Nr5a2 implicated in acute pancreatitis (AP) remains insufficient." (PMID 31992986, 2019). "However, at the same time, in mice, Nr5a2 deficiency leads to an unstable differentiation state of the mature pancreas, pancreatic migration to the ducts, and loss of regenerative capacity after acute pancreatitis." (PMID 38358044, 2024).
colitis (3 papers, 2020 to 2022). Inflammation of the colon. "Several nuclear receptors were specifically downregulated in males (Vdr, Lrh1/Nr5a2, Mr/Nr3c2, Rev-erbβ/Nr1d2, Car/Nr1i3, Esrrg, Lxrα/Nr1h3) and have indeed been demonstrated to regulate key protective functions relating to colitis or CRC." (PMID 36142324, 2022).
Infertility (3 papers, 2015 to 2024). "NR5A2 gene knockout mice showed ovulation dysfunction and infertility, suggesting that NR5A2 is necessary for follicular development and ovulation in mammals." (PMID 35281430, 2021). "Conditional knockout of Nr5a2 in granulosa cells results in infertility, null mice are not able to ovulate due to the failure of preovulatory follicle tissue remodeling caused by abnormally low mRNA levels for proteases implicated in the ovulatory process." (PMID 26445099, 2015).
renal fibrosis (3 papers, 2022 to 2024). A final common manifestation of a wide variety of chronic kidney diseases characterized by glomerulosclerosis and tubulointerstitial fibrosis. "In renal fibrosis, the nuclear receptor subfamily 5 group A member 2 (NR5A2) and Ubc9 are highly expressed in the kidney, while the K224R mutation of SUMOylated NR5A2 fails to upregulate calreticulin to drive fibrosis." (PMID 39697538, 2024). "Second, it would be of interest to evaluate the effect of applying antagonists of NR5A2 on the progress of renal fibrosis." (PMID 36440574, 2022). "While not specifically implicated in S-AKI, NR5A2 regulates the calreticulin gene during renal fibrosis and plays a role in multiple immune pathways including inflammation and tumor-necrosis factor- (TNF) induced cell death." (PMID 39636799, 2024). "We also identified an upstream regulatory mechanism that mediates the transcriptional control of Calreticulin expression during the progression of renal fibrosis, by showing that the druggable orphan nuclear receptor NR5A2 and its SUMOylation is involved in this action." (PMID 36440574, 2022).
schizophrenia (3 papers, 2019 to 2023). A major psychotic disorder characterized by abnormalities in the perception or expression of reality. "ATAC seq studies from the human prefrontal cortex found enriched motifs for NR5A2 target genes in schizophrenia patients (treated with APs) compared with matched case controls." (PMID 36765131, 2023).
bladder cancer (2 papers, 2022 to 2023). "Expectedly, no such differences could be observed for other cancer types, such as lung, breast, and bladder cancer due to low NR5A2 expression levels." (PMID 38012687, 2023).
cervical cancer (2 papers, 2021). A primary or metastatic malignant neoplasm involving the cervix. "Recently, accumulating evidence has also shown the participation of NR5A2 in the pathogenesis of various tumors including cervical cancers." (PMID 33842467, 2021). "In this study, NR5A2 was identified to express differentially between metastatic and non-metastatic tissues of cervical cancers, and may promote the tumorigenesis and metastasis by regulating VIM." (PMID 33842467, 2021).
chronic pancreatitis (2 papers, 2021 to 2024). A chronic inflammatory process causing damage and fibrosis of the pancreatic parenchyma. "The stratification of patients based on NR5A2 expression allows the distinction in two groups, with an association between low levels of NR5A2 and a higher prevalence of chronic pancreatitis and PDA development." (PMID 33669845, 2021).
esophageal cancer (2 papers, 2013 to 2015). A primary or metastatic malignant neoplasm involving the esophagus. "In summary, miR-139-5p was identified as a tumor suppressor gene associated with the risk for esophageal cancer, and a novel mechanism of regulation of NR5A2 protein by miR-139-5p was reported." (PMID 24204738, 2013). "MiR-139-5p was investigated to induce cell cycle arrest in the G0/G1 phase and to suppress the invasive capability of esophageal carcinoma cells by targeting the 3′UTR of oncogenic NR5A2." (PMID 24204738, 2013). "miR-139-5p was found to suppress cell proliferation and invasive capability of esophageal carcinoma cells and induce cell cycle arrest in the G0/G1 phase and in the late apoptosis of cancer cells by targeting oncogenic NR5A2." (PMID 24204738, 2013). "Given that miR-139-5p has been established to regulate NR5A2 expression by binding with the conserved site of NR5A2 in the 3′UTR region, the changes in NR5A2 expression levels are related to the expression changes in miR-139-5p, which was confirmed with four esophageal cancer cell lines." (PMID 24204738, 2013).
glioblastoma (2 papers, 2016 to 2022). The most malignant astrocytic tumor (WHO grade IV). "NR5A2 can bind the same DNA motif and plays crucial role in gonadal development and function and was associated with favorable prognosis in patients with glioblastoma and neuroblastoma tumors." (PMID 35794546, 2022).
intestinal tumor (2 papers, 2022 to 2023). "Intriguingly, when Nr5a2 is haploinsufficient, it results in a reduction of intestinal tumor formation." (PMID 38012687, 2023).
lung adenocarcinoma (2 papers, 2019 to 2024). A carcinoma that arises from the lung and is characterized by the presence of malignant glandular epithelial cells. "Nr5a2 was significantly overexpressed due to copy number increase in lung adenocarcinoma (n = 427) compared to normal lung tissues (n = 449, P < 0.05)." (PMID 30740909, 2019).